GLS2 (glutaminase 2)
Diseases named in the same sentence as GLS2 in open-access papers (continued):
Sharing a sentence is not in itself a finding about the gene and the disease.
hepatocellular carcinoma (continued). "More importantly, in contrast with its tumor suppressive roles in hepatocellular carcinomas, we showed that GLS2 paradoxically coordinates both glutamine-dependent anapleurosis and aerobic glycolysis to sustain cell proliferation and survival of MYCN-amplified neuroblastomas." (PMID 26528759, 2015). "Thus, at least in neuroblastomas and cervical carcinomas, GLS2 appears to promoting an opposite phenotype even though it facilitates the similar metabolic effects as those observed in hepatocellular carcinoma cells." (PMID 26528759, 2015). "Overexpression of GLS2 in hepatocellular carcinoma cells reduced cell growth and colony formation." (PMID 24096582, 2014). "Gls2 has been reported to be downregulated in human hepatocellular carcinomas (HCC)." (PMID 24330717, 2013). "On the other hand, GLS2 is silenced in several cancer cell lines compared with the normal tissue of origin, as it takes place in hepatocellular carcinoma (HCC), colon carcinomas and GBMs, where GLS2 promoter was found to be hypermethylated." (PMID 39796278, 2025). "Inhibition of glutaminolysis by targeting GLS1 or GLS2, for example, reduces LC and hepatocellular carcinoma (HCC) metastases, respectively, through repression of SNAIL." (PMID 35054987, 2022). "Some studies have reported that GLS2 is converted to GLS1 in the process of hepatocellular carcinogenesis, and GLS1 was involved in the migration and invasion of hepatocellular carcinoma cells." (PMID 35401189, 2022). "It is noteworthy that, in human hepatocellular carcinoma, GLS2 expression positively correlates with the level of miR-122, which inhibits GLS expression; moreover, Gls2 expression is lower in liver tissues from miR-122 knockout mice compared to wild-type animals." (PMID 38067269, 2023). "The nuclear receptor liver receptor homolog 1 (LRH-1) (also known as NR5A2) was recently found to have a regulatory role in hepatoma formation, since it was shown to upregulate mitochondrial ALT2/GPT2 and cytosolic AST1/GOT1 aminotransferase isoforms as well as glutaminase 2 (GLS2)." (PMID 30416487, 2018).
glioblastoma (17 papers, 2014 to 2025). The most malignant astrocytic tumor (WHO grade IV). "Likewise, our previous studies revealed that stable transfection of a full cDNA sequence encoding GAB protein (a GLS2 isoform) reduces proliferation and migration of glioblastoma T98G cell line and sensitizes transfected cells (TGAB cells) to the alkylating chemotherapeutics." (PMID 24096582, 2014). "In fact, GLS2 promoter methylation, leading to a deficit in its product, was observed in liver and colon cancer, glioblastoma, and basal-subtype breast tumors." (PMID 38067269, 2023). "Recent studies have conclusively proven that GLS2 is a bona fide tumor suppressor at an organismal level, but mounting evidence indicates that a similar situation also occurs in glioblastoma." (PMID 38067269, 2023). "Kim and colleagues identified GLS2 as a key gene in the regulation of 5-ALA metabolism in glioblastoma." (PMID 38067269, 2023). "An ectopic expression of GLS2 decreased the viability and proliferation of glioblastoma T98G, U87MG and LN229 cells, as well as their ability to form colonies and migrate." (PMID 38067269, 2023). "Another type of neoplasm in which GLS2 appears to exert suppressive properties is glioblastoma, an astrocytic tumor with the highest malignancy grade according to WHO classification (WHO IV)." (PMID 38067269, 2023). "In glioblastoma and cancers of liver and colon, GLS2 expression is lost due to DNA methylation of the GLS2 gene." (PMID 31652551, 2019). "In conclusion, the key finding of this study is that GLS silencing reduces proliferation and viability of glioblastoma cells and strengthen the antiproliferative effect evoked by GLS2 overexpression." (PMID 24096582, 2014). "We investigated how GLS2 expression modifies the metabolism of glioblastoma cells, looking for changes that may explain GLS2’s potential tumour suppressive role." (PMID 39796278, 2025). "Notably, this gene, and particularly its isoform GAC, is overexpressed in glioblastoma while the other gene coding for GA, namely GLS2, is silenced in these tumors." (PMID 39259492, 2024). "Notably, promoter methylation has proved to be a crucial mechanism responsible for the downregulation of GLS2 in glioblastoma." (PMID 38067269, 2023). "Indeed, forced expression of GLS2 into the glioblastoma cell lines U87MG and LN229 sensitizes them to the alkylating agent Temozolomide and H2O2-mediated oxidative stress by suppressing the PI3K/AKT pathway." (PMID 36672360, 2023). "An ectopic GLS2 expression sensitized glioblastoma cells to treatment with TMZ." (PMID 38067269, 2023). "Likewise, the transfection of the GLS2 gene construct into the glioblastoma cell lines (T98G, U87MG, and LN18) resulted in a decrease in PpIX accumulation and lower glow level in the samples." (PMID 35055109, 2022). "From the clinical perspective, it is to be hoped that that combination of modulation of expression and/or activity of GA isoforms arising from GLS and GLS2 gene products may in the future provide a useful treatment modality to prevent glioblastoma growth." (PMID 24096582, 2014). "In glioblastoma cells, another lncRNA, ATXN8 Opposite Strand (ATXN8OS), has been shown to stabilize the GLS2 transcript by recruiting the RNA-binding protein (RBP) ADAR." (PMID 38067269, 2023). "In glioblastoma cells, silencing of GLS induces apoptosis, while overexpression of GLS2 inhibits tumor growth." (PMID 35055109, 2022).
glioblastoma (continued). "In glioblastoma (GBM), the most aggressive brain tumor, GLS is highly expressed and in most cases GLS2 is silenced." (PMID 30669455, 2019). "Furthermore, 5-ALA fluorescence was inversely correlated with GLS2 expression and the NADPH level in glioblastoma tissues." (PMID 38067269, 2023). "GLS2 has been described as a tumor suppressor factor in HCC and glioblastoma." (PMID 34094960, 2021). "Likewise, human glioblastoma T98G cell line expresses high amounts of GLS transcripts, while GLS2 transcripts are hardly detectable in these cells." (PMID 24096582, 2014). "An intriguing question arose whether or not combination of GLS silencing and GLS2 overexpression would increase the inhibition of cell proliferation and survival of glioblastoma cells elicited by individual manipulations." (PMID 24096582, 2014). "In glioblastomas (WHO grade IV), the most malignant brain tumors, high levels of GLS and only traces or lack of GLS2 transcripts were found." (PMID 24096582, 2014). "Interestingly, the expression of GLS is upregulated in glioblastoma compared to non-tumorigenic brain tissues, reinforcing the idea that GLS and GLS2 play opposing roles in certain cancer types." (PMID 38067269, 2023).
glioma (14 papers, 2015 to 2024). A benign or malignant brain and spinal cord tumor that arises from glial cells (astrocytes, oligodendrocytes, ependymal cells). "Importantly, downregulation of GLS2 has been recognized as a hallmark of glioma cells." (PMID 35055109, 2022). "LncRNA ataxin 8 opposite strand (ATXN8OS) has been reported to be a negative regulator of glioma through stabilizing GLS2 mRNA." (PMID 36499136, 2022). "In sharp contrast, the nuclear accrual of GLS2 in neuroblastoma and glioma cells occurs in parallel with cell cycle arrest at the G2/M stage." (PMID 32042057, 2020). "A similar response was obtained by overexpression of GLS2 in T98G glioma cells, including downregulation of oncogene c-Myc." (PMID 32042057, 2020). "A previous research has shown the synergistic role of GLS1 silencing and GLS2 overexpression in apoptosis, antioxidant status and cellular motility in glioma cells." (PMID 25844758, 2015). "Restoring GLS2 expression in T96G glioma cells inhibited cell proliferation, survival, and migration; furthermore, it increased cell sensitivity to alkylating agents like temozolamide (TMZ) and carmustine by downregulating O6-methylguanine-DNA methyltransferase (MGMT)." (PMID 38786726, 2024). "Furthermore, ADAR1 was shown to be involved in the impairment of TMZ resistance in glioma stabilizing glutaminase 2 (GLS2) mRNA, involved in the ferroptosis pathway by lipid metabolism." (PMID 36499683, 2022). "GLS2 potentiates ferroptosis and suppresses the malignant phenotype of gliomas." (PMID 36499136, 2022). "Although some miRNAs have been shown to regulate GA expression in certain types of cancers, it is currently unknown whether similar miRNA mechanisms would contribute to GLS activation and GLS2 repression in gliomas." (PMID 33610185, 2021). "Interestingly, the generation of reactive oxygen species (ROS) by treatment with oxidizing agents, like arsenic trioxide or hydrogen peroxide, synergizes with GLS2 overexpression to suppress malignant properties of T98G glioma cells." (PMID 32042057, 2020). "Consequently, GLS2 upregulation may facilitate chemotherapeutic intervention in addition to inhibiting glioma growth." (PMID 32042057, 2020). "Gene expression analysis detected GLS1 isoforms (KGA and glutaminase C [GAC]), using specific primer sets, and GLS2 mRNA in JHH520, TS603, BT142 glioma neurospheres and in JHH273 xenograft tumor." (PMID 33681764, 2021). "GLS2 mRNA might be stabilized by ATXN8OS through recruiting ADAR, leading to the inhibition of glioma development." (PMID 36499136, 2022). "The upregulation of the GLS2 expression and the inhibition of the PI3K/AKT pathway may become a novel combined therapeutic strategy for anti-glioma preclinical investigations." (PMID 30669455, 2019).
bladder cancer (12 papers, 2017 to 2024). "Urothelial carcinoma-associated 1 inhibited ROS production in bladder cancer cells via dealing with miR-16 and regulating GLS2 expression." (PMID 36483029, 2022). "It has been reported that overexpression of lncRNA urothelial carcinoma-associated 1 (UCA1) promoted the expression of GLS2 in human bladder cancer cells." (PMID 35006436, 2020). "miR-16 directly binds to the 3′UTR of GLS2 mRNA to inhibit bladder cancer growth, whereas lncUCA1 was found to interfere with miR-16’s tumor suppressor role in bladder cancer cells." (PMID 38544804, 2024). "On the other hand, expression of GLS2 by bladder cancer cells was regulated through interfering with miRNA-16." (PMID 33610185, 2021). "UCA1 regulates the expression of GLS2 by interfering with miR-16, and blocked ROS formation in bladder cancer." (PMID 33610185, 2021). "Further study revealed that UCA1 functioned as a miR-16 sponge to reduce ROS production and induce GLS2 expression, leading to increased glutaminolysis in bladder cancer cells." (PMID 35006436, 2020). "Expression of this lncRNA in bladder cancer tissues and cell lines is significantly correlated with GLS2 expression." (PMID 33123468, 2020). "LncRNA urothelial carcinoma-associated 1 (UCA1) interferes the negative regulation of GLS2 mRNA by miR-16, upregulating GLS2 expression to promote glutaminolysis, inhibit ROS production and protect cells from oxidative toxicity in bladder cancer 95-97." (PMID 32174794, 2020). "In contrast, GLS2 methylation was found to be decreased in bladder cancer, but increased in breast, brain GBM, kidney, and prostate cancer." (PMID 30871151, 2019). "LncRNA UCA1 sponges miR-16 to upregulate the expression of glutaminase 2 (GLS2) in bladder cancer." (PMID 34803512, 2021). "Notably, the mRNA level of UCA1 and GLS2 are positively correlated, and the expression of GLS2 is negatively correlated to the miR-16 in bladder cancer." (PMID 33849550, 2021). "Moreover, in bladder cancer cells, by acting as a miR-16 sponge and upregulating the expression of miR-16 targeting GLS2, UCA1 contributes to glutamine metabolism and represses ROS formation in bladder cancer." (PMID 30134946, 2018). "LncRNA-UCA1 via miR-16/GLS2 axis could promote glutamine metabolism in bladder cancer." (PMID 33123468, 2020). "Likewise, GLS2 shows oncogenic behavior in colon, blood, ovarian, thymoma, and bladder cancer." (PMID 30871151, 2019). "UCA1, which is overexpressed in bladder cancer, specifically induces Glutaminase 2 (GLS2) by sponging miR-16, and can also activate AKT by recruiting E1A Binding Protein P300 (EP300) and lead to bladder cancer cell growth." (PMID 34422802, 2021). "In bladder cancer cells, UCA1 regulates the glutamine metabolism and antioxidant defense by inhibiting miR-16, which targets GLS2 for translational inhibiting and reduced GLS2 expression." (PMID 33849550, 2021).
cervical cancer (11 papers, 2015 to 2024). A primary or metastatic malignant neoplasm involving the cervix. "The glutaminase-2 enzyme (GLS2) has been implicated in the radiation response of cervical carcinomas." (PMID 33801846, 2021). "When GLS2 was knocked down, the level of antioxidant glutathione decreased and ROS increased after RT, which promoted the radiosensitivity of cervical cancer cells." (PMID 36313645, 2022). "GLS2 is overexpressed in cervical cancer tissues of radioresistant patients, and in vitro GLS2 knockdown reverses the radioresistant phenotype of different cancer cell lines by reducing GSH and NADH levels, and, therefore, increasing intracellular ROS levels." (PMID 33801846, 2021). "Knock-down of GLS2 increases the intracellular ROS levels, and substantially enhances radiosensitivity of cervical cancer." (PMID 26402672, 2015). "In radioresistant cervical cancer tissues, GLS2 was overexpressed, and silencing GLS2 could reverse this radioresistant phenotype by decreasing GSH and NADH levels." (PMID 36778122, 2023). "Cervical cancer is another malignancy in which the expression of GLS2 is upregulated." (PMID 38067269, 2023). "Similarly, GLS2 content was elevated in radioresistant cervical cancer cells HeLaR compared to the parental HeLa cells." (PMID 38067269, 2023). "However, GLS2 has been shown to play an important role in radioresistance of cervical cancer patients in a recent study." (PMID 26402672, 2015).
liver cancer (10 papers, 2013 to 2025). An epithelial or non-epithelial malignant neoplasm that arises from the liver. "In line with this, Suzuki and colleagues recently demonstrated that Gls2-deficient mice or GLS2-depleted human cancer cells are significantly resistant to ferroptosis and this can contribute to the onset of liver cancer." (PMID 38539832, 2024). "The overexpression of GLS2 in human liver cancer cells induced significant growth, proliferation, ectopic expression, and a G2/M arrest." (PMID 37124062, 2023). "A previous study had demonstrated that the epigenetic silencing of GLS2 by promoter hypermethylation was common in human liver cancer, in accordance with the results observed in our study." (PMID 34573287, 2021). "GLS2 was found to be an important predictor of survival for patients with liver cancer, where this gene is downregulated." (PMID 30871151, 2019). "In contrast, our results showed that GLS2 is over-expressed in bladder and lung cancers, whereas it is downregulated in liver cancer which indicates that glutaminases are indeed differentially expressed in different types of human cancer." (PMID 30871151, 2019). "It has been shown that glutamine metabolism switches from GLS2 to GLS1 in MYC-induced mouse liver cancer." (PMID 25844758, 2015). "Using real-time PCR, reduced level of Gls2 mRNA was found in a group of human liver cancer cells and colon cancer cells when compared to the human normal liver and colon tissues, respectively." (PMID 24330717, 2013). "Such a treatment markedly enhanced Gls2 mRNA level in almost all the selected human liver cancer cells." (PMID 24330717, 2013). "It appears that liver cancers with Gls2 promoter methylation were found to have higher percentage of abnormal AFP and higher TNM stage, although no statistical differences were found, probably due to the relative small sample size." (PMID 24330717, 2013). "The group with DUOX1, GLS2 and FBP1 low expression may have 2.562, 2.540 and 3.529 times risk of liver cancer relapse compared with these genes high expression group." (PMID 27079415, 2016). "In addition, we also attempted to summarize and compare the clinical-pathological characteristics of the 20 liver cancer patients in terms of Gls2 promoter methylation status." (PMID 24330717, 2013). "It is thus believed that detection of Gls2 promoter methylation in liver tissues could be a useful biomarker for diagnosis and prognosis of liver cancer." (PMID 24330717, 2013). "Of note, AKR1B10, ACSL4, GLS2, LCAT, were among the metabolic targets we previously identified as consistent in HCC, indicating a high alteration frequency of these genes across liver cancer datasets." (PMID 30176945, 2018). "What’s more, the scoring system including DUOX1, GLS2 and FBP1 acted as predictive model firstly used in our study to predict HCC patients’ survival and this predictive model can be a potential prognostic tool for liver cancer patients." (PMID 27079415, 2016).